DVL1 (dishevelled segment polarity protein 1)
Diseases named in the same sentence as DVL1 in open-access papers (continued):
Sharing a sentence is not in itself a finding about the gene and the disease.
Umbilical hernia (1 paper, 2021). Protrusion of abdominal contents through a defect in the abdominal wall musculature around the umbilicus. "Vertebral segmentation defects and ribs fusion occur in the recessive form linked to ROR2 mutations (MIM# 268310) whereas umbilical hernia and supernumerary teeth are more common in the autosomal dominant forms due to WNT5A (MIM# 180700), DVL1 (MIM# 616331), DVL3 (MIM# 616894) mutations." (PMID 35096710, 2021).
virus infection (1 paper, 2023). "Our goal was to introduce the wild-type DVL1 using virus infection in the chicken or by transgenesis in the fly and compare the effects to the variant forms and controls." (PMID 36916233, 2023).
tumor (41 papers, 2007 to 2025). "In various cancers, abnormal DVL1 expression is associated with poor prognosis, indicating its relevance in tumor biology." (PMID 40276499, 2025). "Functional analyses, covering CRISPR-Cas9 screening as well as pathway enrichment studies, further highlighted the critical role of DVL1 in cancer biology, with significant enrichment in pathways associated with tumor progression." (PMID 40276499, 2025). "Differential expression analysis further highlights the extensive alteration in gene expression associated with DVL1, implicating its pivotal role in tumor development." (PMID 40276499, 2025). "The ROC curves further confirm the diagnostic and prognostic value of DVL1, with AUC values indicating its potential to distinguish between tumor and normal tissues, and to predict patient outcomes." (PMID 40276499, 2025). "High expression of DVL1 was observed in 55% (33/60) of CRC tumor specimens and was associated significantly with tumor depth, perineural invasion and liver metastasis status (all p < 0.05)." (PMID 24129181, 2013). "It is shown that DVL1 overexpression may enhance the metabolic plasticity of tumor-associated immune cells and cardiomyocytes, leading to abnormal glucose utilization and impaired oxidative phosphorylation, thus aggravating the myocardial energy crisis in SIC." (PMID 40276499, 2025). "DVL1 gene expression levels varied in different organs of cancer patients, and the expression levels varied with the anatomical location of the tumor." (PMID 40276499, 2025). "Thermal profiling data delineate significant covariations between DVL1 transcriptional activity and immunological biomarkers within COAD, establishing mechanistic insights into its regulatory potential within tumor-associated immune landscapes." (PMID 40276499, 2025). "Spatial mapping further accentuates the enhanced expression of DVL1 in malignant areas, indicating its potential engagement in tumor progression and aggression." (PMID 40276499, 2025). "Collectively, these results suggest that DVL1 plays a critical role in promoting cell proliferation and tumor progression, and that down-regulation of its expression by pharmacological agents or gene knockdown significantly inhibits these processes." (PMID 40276499, 2025). "The study investigated the expression of DVL1 and its impact on cell proliferation and tumor progression across various cell lines, including SW620, HCT116, and RAW264.7." (PMID 40276499, 2025). "Spatial transcriptomics provides a refined visualization of DVL1 expression within tumor tissue, revealing its heterogeneous spatial distribution." (PMID 40276499, 2025). "The observed changes in DVL1 phosphorylation sites between normal and tumor tissues suggest possible post-translational modifications contributing to its oncogenic role." (PMID 40276499, 2025). "This suggests that Digoxin-mediated DVL1 downregulation contributes to reduced tumor cell proliferation." (PMID 40276499, 2025). "DVL1 is associated with poor prognosis, DVL2 promotes tumor proliferation and invasion through interaction with PWP1, and DVL3 drives cancer cell invasion and metastasis via Wnt5B-regulated signaling." (PMID 39594618, 2024). "Mechanistically, ATF5 promotes the transcription of disheveled-1 (DVL1), a potent activator of Wnt/β-catenin, and increases tumor sphere formation ability through the ATF5/DVL1/Wnt/β-catenin axis." (PMID 39261452, 2024). "When examining specific primary tumor sites, including the lung, pancreas, small intestine, duodenum, stomach, and rectum, our analysis revealed significant variation in DVL1 concentrations (p < 0.01)." (PMID 39796676, 2024).
tumor (continued). "Significantly, overexpression of DDX5 in HCC xenografts repressed DVL1 expression and increased ferroptosis, resulting in reduced tumor growth by sorafenib." (PMID 38036507, 2023). "Secondly, in sorafenib-treated Huh7 xenografts overexpression of DDX5 suppressed tumor growth and DVL1 expression required for Wnt/β-catenin activation, inducing ferroptosis." (PMID 38036507, 2023). "Dishevelled paralogs (DVL1, 2, 3) are key mediators of Wnt pathway playing a role in constitutive oncogenic signaling influencing the tumor microenvironment." (PMID 36809986, 2023). "All 10 DEGs found in the patients who lived in Sao Paulo city compared to the MRSP were associated with cell proliferation and tumor development (BMP4, CTNNBP1, DISP1, DVL1, ERBB4, PRLR, WNT5b, LEF1, PGR, and PTEN)." (PMID 36768749, 2023). "Our analysis suggests that increased DVL-1 expression correlates with decreased expression levels of several immune cell genes and anti-tumor immune cell signaling regulators such as STAT5B." (PMID 34659647, 2021). "Collectively, these results demonstrate that DVL-1 enhances tumor growth, both in-vitro and in-vivo in TNBC models." (PMID 34733415, 2021). "In order to understand the differential expression of DVL-1 between various tumor types (in red color) and its adjacent normal tissues (in blue color), we analyzed RNA-Seq data from TCGA." (PMID 34659647, 2021). "In vivo experiments further showed DVL1 was crucial to the tumor volume and tumorigenicity in CDX animal model." (PMID 34288405, 2021). "On the contrary, LoVo‐FUBP1 with DVL1 overexpression xenografts recovered the tumor volume and tumorigenicity compared with LoVo‐shFUBP1 xenografts." (PMID 34288405, 2021). "Collectively, these results demonstrate that DVL1-K285Q significantly reduces tumor growth in vivo, possibly by altering Wnt target gene expression in TNBC model." (PMID 34733415, 2021). "In human HNSCC tumor tissues we observed only an increase in the nuclear localization of the Dvl-1 protein." (PMID 32368285, 2020). "In accordance with cell line results expression of the WWOX, DVL-1, DVL-2 and DVL-3 genes were lower (73.5 %, 51%, 56.1% and 50%) in the tumor tissues and the differences were statistically significant." (PMID 32368285, 2020). "While, Dvl-1 protein levels were increased in the nuclei of the tumor tissues, there was a decrease in the nuclear levels of the Dvl-2 and Dvl-3 proteins." (PMID 32368285, 2020). "The results on protein expressions indicated that high‐grade tumours expressed less DVL1 protein as compared with low grade ones." (PMID 30468298, 2019). "Cell count analysis of DVL1 signal strength showed statistically significant differences in the number of cells with low, moderate and strong expression among different tumour grades (P < 0.001)." (PMID 30468298, 2019). "Lower tumour grades (I and II) showed significantly higher levels of DVL1 expression than high grades (III and IV), while strong DVL3 expression was significantly associated to high‐grade tumours." (PMID 30468298, 2019). "Of note, in tumours with low levels of DVL1 expression, the signal was predominantly localized in the cytoplasm or in the cytoplasm and cell membrane." (PMID 30468298, 2019). "Stronger DVL1 expression was associated to low‐grade tumours and strong DVL3 expression to high‐grade tumours." (PMID 30468298, 2019). "In tumours with moderate and strong expression levels of the DVL1 protein, the signal was significantly more frequently localized in cytoplasm and nucleus (P < 0.001)." (PMID 30468298, 2019). "miR-103 was reported to reduce cell proliferation and increase cell apoptosis by targeting the c-Myc activators known as c-Myb and DVL1 in hemopoietic tumor cells." (PMID 30423818, 2018). "Amplification and up-regulation of DVL1 gene are involved in breast carcinogenesis, especially in the acceleration of tumor growth." (PMID 25358879, 2014).
tumor (continued). "This provides insight into the contribution of DVL1 in the transcription of genes involved in various cellular functions, including those that drive triple-negative breast tumorigenesis and modulation of the tumor microenvironment." (PMID 40628704, 2025). "The abnormal activation of MYC may aggravate the inflammatory response in the tumor microenvironment by enhancing DVL1 expression, and the synergistic action of NF- κ B and STAT 3 may further drive the pathological progression of SIC." (PMID 40276499, 2025). "The variations in DVL1 concentrations across different primary tumor sites could have important implications for understanding the pathophysiology of NETs." (PMID 39796676, 2024). "Herein, our findings suggest that DVL-1 may be one of the factors that help the tumor cells to escape anti-tumor immune responses thereby allowing for the proliferation and growth of malignant cells." (PMID 34659647, 2021). "Our study explored DVL1, DVL2 and DVL3 gene alterations in association with tumour grade." (PMID 30468298, 2019). "The expression of DVL1 protein greatly differed among different tumour grades." (PMID 30468298, 2019). "We also noticed that in tumours with low DVL1 expression, the signal was predominantly localized in the cytoplasm or in the cytoplasm and cell membrane, while in those with moderate and strong expression, the signal was confined to cytoplasm and nucleus (P < 0.001)." (PMID 30468298, 2019). "Collectively, our findings provide additional insights into the contribution of DVL-1 in triple-negative breast tumorigenesis as well as suggests that nuclear DVL-1 could modulate tumor microenvironment by transcriptionally regulating genes involved in various cellular functions." (PMID 34659647, 2021). "However, we detected an increase only in the nuclear localization of Dvl-1 in tumor tissues." (PMID 32368285, 2020). "In this research, we probed into the function of the DVL1 in COAD, concentrating on its expression patterns among tumor stages and its connection with key cancer-related pathways." (PMID 40276499, 2025). "Correlation analysis between DVL1 and ATF5 suggests a regulatory interaction, potentially impacting tumor progression." (PMID 40276499, 2025). "Analysis of DVL1 expression in four gastrointestinal tumors - COAD, STAD, ESCA and READ - showed significant overexpression in tumor tissues compared to normal tissues." (PMID 40276499, 2025). "We found that the expression of NPHP3, DVL1, and DVL3 was significantly higher and the expression of ANKS6 was significantly lower in the primary tumor in comparison to the normal solid tissue." (PMID 39596188, 2024). "Elevated levels of these proteins highlight their importance in tumor biology, with SFRP3 and DVL1 potentially being crucial in NET molecular mechanisms." (PMID 39796676, 2024). "The expressions of DVL1, MRPL4, and NSUN3 were relatively higher, while that of RPH3A was relatively lower in the tumor tissues." (PMID 36035311, 2022). "It showed that SW48‐FUBP1 with DVL1 knockdown and treatment with NSC668036 in SW48‐FUBP1 xenografts inhibited the tumor volume and tumorigenicity significantly." (PMID 34288405, 2021). "Expression rates of DVL1 and DVL3 were higher in the SCC-15 tumor cell line compared to the HET-1A normal cell line." (PMID 32368285, 2020). "The variability in DVL1 expression across tumor cell states and pathway activity differences between DVL1-positive and DVL1-negative cells emphasize the gene’s influence on tumor heterogeneity and pathway activation." (PMID 40276499, 2025). "We assessed the correlation of INVS and genes of interest in its interactome (NPHP3, DVL1, DVL3, and ANKS6) with tumor immune infiltration and expression using different algorithms (XCELL, TIMER, QUANTISEQ, EPIC, CIBERSORT, CIBERSORT-ABS, and MCPCOUNTER) by using GEPIA." (PMID 39596188, 2024).
tumor (continued). "The elevated serum concentrations of SFRP3 in NET patients, along with the higher DVL1 levels in BP-NETs compared to GEP-NETs, suggest that these proteins may play crucial roles in tumor biology." (PMID 39796676, 2024). "By identifying the specific patterns of DVL1 concentration, clinicians could improve the accuracy of NET diagnosis and potentially tailor treatments based on the tumor’s primary site." (PMID 39796676, 2024). "Moreover, FUBP1 increased the protein expression of DVL1 in CRC cells and tumor specimens, while silencing FUBP1 had the reverse effects." (PMID 34288405, 2021). "Finally, we identified immunoreactivity of DVL1 in the cytoplasm of tumor cells of 60 CRC patients and evaluated the relationship between DVL1 expression and liver metastasis status using immunohistochemical (IHC) staining." (PMID 24129181, 2013). "Therefore, we conclude that PPARD's activation on DVL1 leads to repressing PPARG's activity, and this gives clues for tumour repressor PPARG's inactivation and leads to cancer progression into the HR stage." (PMID 19640296, 2009). "Therefore, it could be possible that DVL1 and DVL3 are only targeted by miR-1247-5p specifically in the adrenal of CPA and PBMAH patients, leading to its characterized tumor progression." (PMID 35887024, 2022). "Furthermore, we wanted to evaluate whether DVL-1 regulates target genes such as STAT5B, which has been shown to play a critical role in cancer and anti-tumor immunity." (PMID 34659647, 2021). "Furthermore, mRNA expression studies, demonstrate a negative correlation between DVL-1 expression and the markers for T cell exhaustion (e.g. CTLA4, HAVCR2), CD8+ T cell (CD8B), tumor-associated macrophages (TAM), T helper cell, and dendritic cells." (PMID 34659647, 2021). "We also observed a fold increase in the expression of DVL1 (and BTRC to a lesser extent) in TN tumor samples as compared to non-TN tumor samples." (PMID 24143235, 2013). "In BCPAP cells treated for 72 h, genes from the canonical Wnt pathway (FZD1, DVL1, AKT2, CTNNB1, LEF1, MYC) and the non-canonical Wnt pathway (RHOA, related to cytoskeletal dynamics and increased migration and invasion) were upregulated, suggesting pro-tumor behavior." (PMID 39125748, 2024).
cancer (39 papers, 2007 to 2025). A tumor composed of atypical neoplastic, often pleomorphic cells that invade other tissues. "Our results demonstrate that DVL-1 is highly expressed in triple-negative BC compared to non-cancer tissues and associated with various clinical factors that may contribute to poor prognosis and survival rate." (PMID 34659647, 2021). "In addition, we performed 3D-spheroid assay to understand the role of DVL-1 and key lysines in regulating this cancer hallmark." (PMID 34733415, 2021). "We also identify that acetylation of two key lysine residues, K69 and K285, present on the DIX and PDZ domains respectively, promote nuclear over cytoplasmic localization of DVL-1, and influences its promoter binding and regulation of genes implicated in cancer." (PMID 31700102, 2019). "The genes regulated by DVL1 extended across all compartments of the cell (nucleus, nuclear membrane, cytoplasm, extracellular membrane) as well as genes associated with the transcription regulator complex and affected pathologies related to both development and cancer." (PMID 40628704, 2025). "Furthermore, we uncover the role of three lysines on structural domains of DVL-1 and characterize their impact on several fundamental cellular processes such as transcription of stem-cell and cancer-associated genes, 3D-spheroid growth, cell migration, and cell cycle progression." (PMID 34733415, 2021). "This study highlights DVL1 as a key gene in SIC and its association with poor outcomes in cancer, particularly in the context of immunotherapy resistance." (PMID 40276499, 2025). "Through the utilization of the datasets, we discovered the core gene DVL1 that exhibited remarkable up-regulated expression both in SIC and in diverse kinds of cancers, which were associated with poor prognosis and inflammatory responses." (PMID 40276499, 2025). "Kaplan-Meier survival curves indicated that elevated DVL1 expression correlates with poorer survival outcomes in these cancers, suggesting its value as a prognostic marker." (PMID 40276499, 2025). "Recently, our group showed that DVL-1 proteins are highly expressed in TNBC compared to non-cancer samples." (PMID 34659647, 2021). "These cancers can be caused by single mutations (germline or mosaic) in, for example, APC or WTX, but also common genetic variation in WNT3, DVL1, and NXN is previously associated with increased cancer risk." (PMID 32328030, 2020). "We previously reported that SIRT-1, a class III lysine deacetylase, positively regulates DVL-1 proteins levels in cancer cells." (PMID 31700102, 2019). "There was also a concomitant decrease (2.5 fold) in mRNA transcript of CTNNB1 and other elements of Wnt/β-catenin signaling (e.g. axin, DVL1, GSK3β) in cancer cells compared to normal cells." (PMID 20454608, 2010). "This study revealed the critical role of DVL1 gene in SIC in cancer patients." (PMID 40276499, 2025). "In cancer metabolism, DVL1 may regulate glycolysis and mitochondrial bioenergetic metabolism through the Wnt signaling pathway." (PMID 40276499, 2025). "Since DVL relays oncogenic input signals, we hypothesized that the expression levels of DVL-1 would be high in various cancer types." (PMID 34659647, 2021). "We next investigated the impact of DVL-1 on cancer hallmarks in TNBC models." (PMID 34733415, 2021). "In addition, to further validate the expression of DVL-1 protein in patient tissues, we used the pathology images from the HPA database, where DVL-1 is stained in normal and cancer tissues using antibody CAB011538." (PMID 34659647, 2021). "Overall, our findings emphasize the importance of DVL-1 with TNBC-related pathology and identified unexpected gene targets of DVL-1, that may help explain the complexity of aberrant Wnt signaling in cancer." (PMID 34659647, 2021).